IL26 (interleukin 26)
Diseases named in the same sentence as IL26 in open-access papers (continued):
Sharing a sentence is not in itself a finding about the gene and the disease.
autoimmune disease (10 papers, 2018 to 2025). A disorder resulting from loss of function or tissue destruction of an organ or multiple organs, arising from humoral or cellular immune responses of the individual to their own tissue constituents. "IL-26 has a unique ability to bind extracellular DNA released by dying cells, a property particularly relevant in chronic inflammatory and autoimmune diseases." (PMID 41516201, 2025). "As a product of Th17 lymphocytes, IL-26 not only helps Th17 cells mitigate infections due to direct antimicrobial activity, but it can also be a driver and effector of inflammation in autoimmune diseases." (PMID 39272777, 2024). "IL-26 is a member of the IL-10 cytokine family and plays a key regulatory role in multiple chronic inflammations and autoimmune diseases." (PMID 35902909, 2022). "Several genetic studies have suggested a potential role for IL-26 in the pathophysiology of chronic inflammatory and autoimmune disorders." (PMID 30809226, 2019). "High levels of AK155(IL-26) expression are seen in autoimmune disorders mediated by TH17 cells." (PMID 40149591, 2025). "IL26 is a key cytokine involved in immune cell priming, antibacterial immunity, and autoimmune diseases produced by RORγt expressing Th17 cells, but not previously shown to be directly regulated by RORγt." (PMID 30184180, 2018).
gastric cancer (9 papers, 2020 to 2025). A primary or metastatic malignant neoplasm involving the stomach. "Elevated serum levels of IL-26 have been implicated in gastric cancer, in which higher serum IL-26 strongly correlates with disease stage." (PMID 41516201, 2025). "The primary cellular source of IL-26, Th17 cells, is evidently linked to gastric cancer." (PMID 41516201, 2025). "A possible explanation for this association is provided by Wang and colleagues, who demonstrated that stimulation of gastric cancer cells with IL-26 significantly enhanced cell proliferation." (PMID 41516201, 2025). "Recently, a study showed that serum IL-26 levels were closely related to gastric cancer and its clinicopathological stages." (PMID 35902909, 2022). "The serum IL-26 level is closely correlated with gastric cancer and has important value for the determination of disease occurrence and development." (PMID 34621670, 2021). "IL-20 and IL-26 were discovered to promote proliferation and migration of bladder cancer, breast cancer, and gastric cancer cells, while IL-24 was found to inhibit the proliferation and metastasis of melanoma, prostate cancer, and OC." (PMID 34114949, 2021). "There is, however, evidence that IL26 promotes the proliferation and survival of gastric cancer cells." (PMID 31948053, 2020). "Based on transcriptome data analysis revealing elevated expression of IL17A and IL26 in gastric cancer tissues, we systematically evaluated the impact of these two cytokines on malignant biological behaviors of GC tumor cells through in vitro functional experiments." (PMID 40452847, 2025). "Subsequently, we demonstrated through CCK-8 assays, scratch wound healing assays, and Transwell invasion assays that both IL-17A and IL-26 significantly enhanced the proliferation, migration, and invasive capacities of gastric cancer cells, thereby facilitating gastric cancer progression." (PMID 40452847, 2025). "IL-17 cells may promote tumor progression through IL-17, IL-22, and IL-26 signaling pathways; thus, targeting IL-17 cells and related signaling pathways may serve as a therapeutic strategy for gastric cancer." (PMID 39676857, 2024). "Our study elucidates the immunosuppressive role of Tc17 cells in the gastric cancer microenvironment, particularly their recruitment by tumor cells via the CXCL16-CXCR6 axis and subsequent promotion of tumor progression through the secretion of cytokines such as IL-17A and IL-26." (PMID 40452847, 2025).
COVID-19 (8 papers, 2021 to 2025). A disease caused by infection with severe acute respiratory syndrome coronavirus 2. "In doing so, we obtained evidence that systemic IL-26 associates with all the referred aspects of COVID-19, including respiratory comorbidity, thereby reinforcing the potential of systemic IL-26 as a target with clinical utility." (PMID 39430762, 2024). "A higher concentration of dsDNA in plasma, which suggests increased NET production and/or tissue damage, was associated with more severe COVID-19 and a higher concentration of IL-26." (PMID 39430762, 2024). "Along these lines, we have previously reported an increase in the plasma concentration of IL-26 among patients with acute COVID-19 that is linked to harmful hyperinflammation." (PMID 39430762, 2024). "In doing so, we obtained strong evidence that the kinocidin IL-26 is increased at the systemic level and associates with several markers of hyperinflammation and tissue damage in acute COVID-19." (PMID 36466824, 2022). "In addition, we recently published evidence that systemic IL-26 is markedly increased in patients with acute coronavirus disease 2019 (COVID-19), and that this increase associates with hyperinflammation and tissue damage." (PMID 39430762, 2024). "Thus, IL-26 bears both antiviral and pathogenic relevance in COVID-19 and, given its accessibility in blood, it may constitute a potential target for clinical diagnosis, monitoring and treatment of this dangerous disease." (PMID 39430762, 2024). "Thus, our findings indicate that increased systemic IL-26 associates with markers of hyperinflammation and tissue damage in patients with acute COVID-19, thereby forwarding the kinocidin IL-26 as a potential target for diagnosis, monitoring, and therapy in this deadly disease." (PMID 36466824, 2022). "Provided that IL-26 expression significantly correlates with the severity of COVID-19 infection, the potential functional involvement of IL-26 in COVID-19 can be suspected." (PMID 41516201, 2025). "Second, we found that the plasma concentration of IL-26 is higher in male patients with COVID-19 than in female patients." (PMID 39430762, 2024). "We found that patients with severe/critical COVID-19 and males were 3.420 and 2.552 times more likely to have an IL-26 measurement (ELISA) above the LLOD than patients with mild/moderate COVID-19 and females, respectively." (PMID 39430762, 2024). "IL-26 was quantified using ELISA in plasma samples from a large cohort of well-characterized patients with acute COVID-19 (n=178) and healthy controls (n=30)." (PMID 39430762, 2024). "Systemic IL-26 is involved in severe COVID-19, especially in males and patients with comorbid obstructive lung disease." (PMID 39430762, 2024). "In the present study, we utilized a large cohort of patients with acute COVID-19 and healthy controls to characterize how systemic IL-26 relates to disease severity, sex and comorbidities." (PMID 39430762, 2024). "In summary, our novel results link enhanced systemic IL-26 to severity of disease, male sex, and respiratory comorbidity in acute COVID-19." (PMID 39430762, 2024). "The plasma concentration of IL-26 was increased in patients with severe/critical COVID-19, particularly among males and patients with comorbid obstructive lung disease." (PMID 39430762, 2024). "Taken together, these findings highlight the potential of systemic IL-26 as a target for therapy in COVID-19." (PMID 39430762, 2024). "Given that we also see an increase in systemic IL-26 in patients with severe/critical COVID-19, our results motivate further research into potential associations between increased IL-26 and patient mortality." (PMID 39430762, 2024). "Of note, samples from patients with mild COVID-19 were excluded from this analysis given that only 1 of them had an IL-26 concentration above the lower limit of detection." (PMID 39430762, 2024).
COVID-19 (continued). "The concentrations of IL-26 in plasma were higher in patients with severe/critical COVID-19 compared to those with mild and moderate disease, as well as to healthy controls." (PMID 39430762, 2024). "Now, in the current study, we found that the enhanced plasma concentration of IL-26 displays a strong correlation with that of IL-8, and a somewhat weaker one with that of TNFα, in the COVID-19 group." (PMID 36466824, 2022). "Here, we characterized the involvement of IL-26 in the hyperinflammation and tissue damage that occurs in patients with acute COVID-19." (PMID 36466824, 2022). "The concentration of IL-26 in plasma was significantly increased in the COVID-19 group compared to the Control group." (PMID 36466824, 2022). "Among the different markers of inflammation and tissue damage analyzed in the COVID-19 group, we proved a positive correlation between the plasma concentration of IL-26 and that of LDH, an established marker of tissue damage." (PMID 36466824, 2022). "Taken together, these findings are suggestive of a mechanistic link between IL-26 and severe COVID-19 that deserves further investigation in larger study materials." (PMID 36466824, 2022). "We think that their uncontrolled approach contributed to the failure to obtain evidence for the involvement of IL-26 in COVID-19." (PMID 36466824, 2022). "From an immunological point-of-view, it is feasible that IL-26 is involved in acute COVID-19, given its dual role as an antiviral and neutrophil-mobilizing mediator of host defense." (PMID 36466824, 2022). "Importantly, patients with COVID-19 who took corticosteroids as part of their treatment had similar plasma concentrations of IL-26 and a similar number of measurements above the LLOD (χ2 test: p = 0.3608) than those who did not receive corticosteroids." (PMID 39430762, 2024). "To determine whether a higher viral load was linked to an increase in IL-26, we first quantified the plasma concentrations of two SARS-CoV-2 antigens in patients with COVID-19." (PMID 39430762, 2024). "Nevertheless, in our study we have focused on systemic alterations in IL-26 during acute COVID-19 and it is possible that the inflammatory profile in the airways of these patients might look different." (PMID 39430762, 2024). "Nevertheless, it is still unclear whether this systemic increase in IL-26 relates to disease severity, sex, comorbidities, viral load, or the innate immune response in acute COVID-19." (PMID 39430762, 2024). "In addition, the concentration of IL-26 in plasma displayed positive correlations with disease severity and length of hospital stay in patients with COVID-19." (PMID 39430762, 2024). "Moreover, the plasma concentration of IL-26 displayed positive correlations with both markers of viral load in patients with COVID-19." (PMID 39430762, 2024). "Indeed, in the current study, we found that the plasma concentration of IL-26 correlates with those of double-stranded DNA (dsDNA) and cell-free nucleosomes when the COVID-19 and Control groups were pooled together for analysis." (PMID 36466824, 2022). "Furthermore, we did not detect a statistically significant correlation between the plasma concentration of IL-26 and age within the COVID-19 or Control groups." (PMID 36466824, 2022). "Moreover, the increase in blood IL-26 correlates with enhanced surface expression of the “don’t eat me” signal CD47 on blood neutrophils isolated from patients with acute COVID-19." (PMID 36466824, 2022). "Moreover, the IL-26 concentration displayed a modest positive correlation (r = 0.36) with that of IL-6 when all the subjects in the COVID-19 and Control groups were pooled together." (PMID 36466824, 2022). "Finally, we also determined the correlation between the plasma concentration of IL-26 and different markers of tissue damage and inflammation, as well as hematological parameters relevant to COVID-19." (PMID 36466824, 2022).
COVID-19 (continued). "Notably, the concentration of IL-26 was still increased in a statistically significant manner in the COVID-19 group compared to the Control group when age matched subjects (30-61 years of age) were investigated." (PMID 36466824, 2022). "Therefore, IL-26 seems likely to play complementary antiviral functions in COVID-19." (PMID 39430762, 2024). "In addition, exclusion of samples with an IL-26 concentration below the LLOD revealed that samples collected within 9 days from onset of symptoms had a higher IL-26 concentration than those collected afterwards in patients with severe/critical COVID-19 exclusively." (PMID 39430762, 2024). "Therefore, in the current pilot study, we quantified the concentration of IL-26 in plasma samples from patients with acute COVID-19 (COVID-19 group), compared with healthy control subjects (Control group), and analyzed its association with the neutrophil-mobilizing cytokines IL-6, IL-8, and TNFα." (PMID 36466824, 2022). "A similar increase in IL-26 concentrations and number of samples above the LLOD (χ2 test: p = 0.0634) was observed for obstructive lung disease in patients with severe/critical COVID-19." (PMID 39430762, 2024). "In essence, the results of the current study substantially expand the evidence that IL-26 participates in the immune response against SARS-CoV-2, as well as in the hyperinflammation that characterizes severe cases of COVID-19, in several different ways." (PMID 39430762, 2024). "Because IL-26 can bind and enhance the inflammatory potential of extracellular DNA, we characterized the relationship between the plasma concentration of IL-26 and markers of NET formation in the COVID-19 and Control groups." (PMID 36466824, 2022). "Based on this evidence, the potential influential role of NETs and their by-products in COVID-19 pathogenesis and outcome is now rapidly gaining acceptance and has also been considered in treatment approaches in COVID-19 such as anti-IL6 and IL26 therapy." (PMID 34367376, 2021). "Serum IL-26, a cytokine involved in IL-17 pathway, TSLP and adiponectin were measured and correlated to lipid COVID-19 patient profiles." (PMID 33536486, 2021). "Interestingly, among the cytokines investigated, only IL-26 (r = 0.40) and IL-8 (r = 0.49) displayed a positive correlation with CD47 expression in blood neutrophils from the COVID-19 group." (PMID 36466824, 2022). "Moreover, we found that IL-8 and IL-26 display comparable correlations with CD47, a marker of neutrophil prolonged survival, in the COVID-19 group." (PMID 36466824, 2022). "Despite its inherent antiviral and neutrophil-mobilizing properties, the involvement of IL-26 in COVID-19 has not been investigated in a conclusive manner." (PMID 36466824, 2022). "Notably, we found that the concentration of IL-26 correlated in a positive manner with that of lactate dehydrogenase (LDH), a marker of tissue damage, in plasma from the COVID-19 group." (PMID 36466824, 2022). "Taken together, our findings support the notion that increased systemic IL-26 might enhance the harmful pro-inflammatory potential of extracellular dsDNA regardless of its origin during acute COVID-19." (PMID 39430762, 2024). "Moreover, the number of plasma samples with a concentration of IL-26 above the lower limit of detection (LLOD) increased from 10% in samples from healthy controls and patients with mild COVID-19, to 30 and 55% in samples from patients with moderate and severe/critical COVID-19, respectively." (PMID 39430762, 2024). "Notably, the concentrations of IL-26 in plasma were higher in males than in females with COVID-19 and the number of plasma samples with a concentration of IL-26 above the LLOD were higher (χ2 test: p = 0.0187) in males than in females with COVID-19." (PMID 39430762, 2024). "However, the role of IL-26 in COVID-19 has not been thoroughly investigated." (PMID 36466824, 2022).
COVID-19 (continued). "In the present study, we found that although the concentration of IL-26 did not correlate with the surface expression of CD11b in any group, it correlated with the surface expression of CD66b and the percentage of CD49d+ neutrophils when the COVID-19 and Control groups were pooled for analysis." (PMID 36466824, 2022). "In addition, the plasma concentrations of both IL-26 and IL-8 displayed a negative correlation with the mean corpuscular hemoglobin (MCH) in whole blood from the COVID-19 group, while IL-6 and TNFα failed to correlate with MCH in this way." (PMID 36466824, 2022).
pancreatic cancer (8 papers, 2020 to 2024). "In pancreatic cancer cells, miR-3607-3p in NK-EVs suppresses cell migration and invasion through downregulation of IL-26, while a decrease in miR-3607-3p levels is associated with poor prognosis and tumor metastasis." (PMID 35501802, 2022). "MiR-3607-3p in NK-Exos prevents the further invasion of pancreatic cancer cells via targeting IL-26." (PMID 37543612, 2023). "IL-26 was found to be a direct target of miR-3607-3p in pancreatic cancer cells, which is highly expressed in pancreatic cancer tissues." (PMID 35501802, 2022). "miR-3607-3p was found to inhibit proliferation, migration, and invasion of pancreatic cancer cells, potentially by targeting IL-26." (PMID 34368150, 2021). "NK-exos miR-3607-3p inhibits pancreatic cancer progression by targeting IL-26." (PMID 37484408, 2023). "Moreover, miR-3607-3p in NKEVs reduced the mRNA and protein levels of IL-26, which is known to play a role in cancer cell proliferation and metastasis and is highly expressed in pancreatic cancer tissues." (PMID 34093547, 2021). "However, whether the inhibitory effects of NKEVs on pancreatic cancer cells depend on the inhibition of IL-26 or other mechanisms remains to be determined." (PMID 34093547, 2021). "In pancreatic tumor tissue as well as in pancreatic tumor cell lines, IL10RB and IL20RA were co-expressed and enable IL26 signaling." (PMID 31948053, 2020). "The biotin-RNA pull-down assay and reporter assay data showed that NK-Exos-loaded miR-3607-3p could target the IL-26 expressed in the pancreatic TME, inhibiting growth and the development of pancreatic tumor cells in vitro and in vivo." (PMID 37543612, 2023). "Pancreatic cancers—but not healthy pancreatic tissue—expressed receptors for IL21 and IL26, a finding that could be confirmed in pancreatic cell lines." (PMID 31948053, 2020).
spondyloarthritis (8 papers, 2012 to 2025). "Beyond RA, elevated IL-26 concentrations have also been observed in the synovial fluid of patients with spondyloarthritis, supporting a broader role for IL-26 in inflammatory joint diseases." (PMID 41516201, 2025). "As osteoproliferation and Th17 cells are important factors in the pathogenesis of axial spondyloarthritis (axSpA), we aimed to clarify the cellular sources of IL26 in spondyloarthritis." (PMID 38799447, 2024). "A recent study confirms the expression of IL-26 by α smooth muscle actin-expressing myofibroblasts in spondyloarthritis patients." (PMID 30809226, 2019). "The role of IL-26 in inflammatory articular diseases has been recently confirmed in a study showing that the levels of IL-26 are increased in the synovial fluids of patients suffering from spondyloarthritis." (PMID 30809226, 2019). "Recent studies have revealed IL-26 expression in a number of other cell types, including alveolar macrophages, bronchial epithelial cells, synoviolin+ synovial cells from RA patients, and myofibroblasts of spondyloarthritis patients suggesting that IL-26 production occurs in multiple cell types." (PMID 30319661, 2018).
atopic dermatitis (5 papers, 2021 to 2025). "A recent report indicated the pivotal role of IL-26 in bridging the Th17 and Th2 immune response in the development of atopic dermatitis." (PMID 38792803, 2024).